LDLRAP1 (low density lipoprotein receptor adaptor protein 1)
Description:
May be required for LDL binding and internalization but not for receptor clustering in coated pits. Binds to phosphoinositides, which regulate clathrin bud assembly at the cell surface. Required for trafficking of LRP2 to the endocytic recycling compartment which is necessary for LRP2 proteolysis, releasing a tail fragment which translocates to the nucleus and mediates transcriptional repression (By similarity).
Synonyms: ARH; ARH2; FHCB1; FHCB2; MGC34705; DKFZp586D0624; ARH1; FHCL4
Tractability: Antibody: its Gene Ontology location is reachable by antibodies, with high confidence. PROTAC: ubiquitination databases record sites on it.
Gene: Protein-coding gene on chromosome 1 (25,543,573 to 25,591,200, forward strand). Ensembl gene ENSG00000157978.
Subcellular location: Cytoplasm
Subcellular location (Human Protein Atlas): Microtubules
Pathways (Reactome):
Metabolism: Transport of RCbl within the body; Vitamin D (calciferol) metabolism
Transport of small molecules: Chylomicron clearance; LDL clearance
Vesicle-mediated transport: Cargo recognition for clathrin-mediated endocytosis; Clathrin-mediated endocytosis
Gene Ontology:
Molecular function: amyloid-beta binding; AP-1 adaptor complex binding; AP-2 adaptor complex binding; clathrin adaptor activity; clathrin binding; low-density lipoprotein particle receptor binding; phosphatidylinositol-4,5-bisphosphate binding; phosphotyrosine residue binding; protein binding; signaling adaptor activity; signaling receptor complex adaptor activity
Biological process: amyloid precursor protein metabolic process; cellular response to cytokine stimulus; cholesterol homeostasis; low-density lipoprotein particle clearance; positive regulation of low-density lipoprotein particle clearance; positive regulation of receptor-mediated endocytosis; positive regulation of receptor-mediated endocytosis involved in cholesterol transport; positive regulation of vascular associated smooth muscle cell proliferation; receptor internalization; receptor-mediated endocytosis; receptor-mediated endocytosis involved in cholesterol transport; regulation of protein binding; regulation of protein localization to plasma membrane; cholesterol metabolic process; cholesterol transport; positive regulation of cholesterol metabolic process
Cellular component: basal plasma membrane; cytoplasmic side of plasma membrane; cytosol; early endosome; recycling endosome; axon; clathrin-coated endocytic vesicle membrane; neurofilament; plasma membrane; cytoplasm
Genetic constraint (gnomAD): Loss-of-function variants: 29 observed, 36.52 expected, observed/expected ratio (o/e) 0.79, 90% interval 0.59 to 1.08. The upper end of that interval is the gene's LOEUF score, 1.08, which puts it in group 4 of 6, group 1 being the genes least tolerant of losing a copy. Missense variants: 374 observed, 400.85 expected, observed/expected ratio (o/e) 0.93, 90% interval 0.86 to 1.02. Synonymous variants: 156 observed, 165.26 expected, observed/expected ratio (o/e) 0.94, 90% interval 0.83 to 1.08.
Gene-disease validity (ClinGen):
ClinGen rates the evidence that LDLRAP1 causes each of these diseases.
hypercholesterolemia, familial, 4 (autosomal recessive): Definitive.
Homologues: Orthologues: chimpanzee LDLRAP1 (99% identical), dog LDLRAP1 (94% identical), pig LDLRAP1 (93% identical), macaque LDLRAP1 (90% identical), mouse Ldlrap1 (90% identical), guinea pig LDLRAP1 (88% identical), rabbit LDLRAP1 (81% identical), rat Ldlrap1 (79% identical), tropical clawed frog ldlrap1 (72% identical), zebrafish ldlrap1b (69% identical), Drosophila melanogaster CG42673 (22% identical), Drosophila melanogaster Dab (21% identical), and 8 more. Paralogues in human: NUMB (23% identical), NUMBL (22% identical), DAB1 (20% identical), NOS1AP (19% identical), DAB2 (18% identical), FAM43A (18% identical), FAM43B (17% identical), MAPK8IP2 (9% identical), MAPK8IP1 (8% identical), GULP1 (5% identical), C1orf226 (3% identical).